PGF (placental growth factor)
Diseases named in the same sentence as PGF in open-access papers (continued):
Sharing a sentence is not in itself a finding about the gene and the disease.
placental disorders (7 papers, 2015 to 2022). "Placental growth factor (PlGF) is an angiogenic factor identified in the maternal circulation, and a key biomarker for the diagnosis and management of placental disorders." (PMID 31924819, 2020). "In this study, we examine the expression of soluble Fms-like tyrosine kinase 1 (sFLT-1) and placental growth factor (PlGF) in EVs-EXs isolated from maternal plasma, in PTB as compared to typical control (Ctrl) pregnancies, as PTB is considered to be a placental disease." (PMID 36619545, 2022).
prostate carcinoma (7 papers, 2013 to 2024). A carcinoma that arises from epithelial cells of the prostate gland. "Of these, PRLR has been implicated in the pathology of breast and prostate cancer, NOX1 expression may be increased in prostate cancer with an important role in angiogenesis, cell growth, and tumor pathogenesis, and both AMH and PGF are reported as crucial genes in tumorigenesis." (PMID 35741849, 2022).
cognitive decline (6 papers, 2021 to 2026). "Within the prefrontal cortex, higher expression of these four genes (VEGFB, FLT1, PGF, and FLT4) was associated with more rapid cognitive decline and higher pathology burden." (PMID 39641382, 2025). "Prefrontal cortex expression of multiple VEGF genes, including ligand genes VEGFB and PGF and receptor genes FLT1 and FLT4, were associated with a more rapid rate of cognitive decline late in life, with VEGFB and FLT4 also associated with cognitive scores closest to death." (PMID 31332262, 2021). "When we expanded our analyses to brain tissues we observed that VEGFB, FLT1, PGF, and FLT4 all appear to contribute to the progression of AD pathology and cognitive decline." (PMID 39641382, 2025).
Insulin resistance (6 papers, 2017 to 2024). Increased resistance towards insulin, that is, diminished effectiveness of insulin in reducing blood glucose levels. "Studies in placental growth factor (PlGF)-deficient mice suggest that reduced PlGF, as is observed in pre-eclampsia in humans, is associated with impaired adipose tissue development and vascularisation and the development of insulin resistance." (PMID 34131300, 2021).
Sepsis (6 papers, 2011 to 2025). Sepsis is defined as life-threatening organ dysfunction caused by a dysregulated host response to infection. "Placental Growth Factor (PlGF) was first identified in the placenta and is up-regulated in several pathological conditions such as tumor malignancy, sepsis, arthritis, and diabetic retinopathy." (PMID 38704457, 2024). "Procalcitonin (PCT), placental growth factor (PlGF) and soluble fms-like tyrosine kinase-1 raise interest for sepsis diagnosis and prognosis." (PMID 34871241, 2021).
type 1 diabetes (6 papers, 2016 to 2025). "It has been demonstrated that placental growth factor (PlGF) concentration dynamics is impaired in women with type 1 diabetes whose fetuses later develop SGA." (PMID 26983627, 2016).
endometrial cancer (5 papers, 2013 to 2025). Primary or metastatic malignant neoplasm involving the endometrium (mucous membrane that lines the endometrial cavity). "Previous studies have shown that pregnancy reduces the risk of endometrial cancer by reducing estrogen exposure; however, it has been reported that some pregnancy-related factors, such as placental growth factor (PlGF) and placenta-specific protein 1 (PLAC-1), are associated with endometrial cancer." (PMID 30921436, 2019).
larynx carcinoma (5 papers, 2015 to 2020). A primary or metastatic malignant neoplasm involving the larynx. "Moreover, placental growth factor (PLGF) secreted by larynx carcinoma (LC) cells triggered M2 polarization of macrophages via transforming growth factor (TGF) β receptor activation, and thereby promoted LC growth." (PMID 27783989, 2016).
liver fibrosis (5 papers, 2016 to 2019). "Placental growth factor (PlGF), a member of the vascular endothelial growth factor (VEGF) family, mediates wound healing and inflammatory responses, exerting an effect on liver fibrosis and angiogenesis; however, the precise mechanism remains unclear." (PMID 28744285, 2017).
osteosarcoma (5 papers, 2002 to 2022). A usually aggressive malignant bone-forming mesenchymal neoplasm, predominantly affecting adolescents and young adults. "Therefore, PGF plays an important role in osteosarcoma progression and may serve as a potential prognostic biomarker." (PMID 35463956, 2022). "Therefore, down‐regulation of PGF by sorafenib might be an important mechanism by which sorafenib inhibits osteosarcoma and PGF might act as a significant therapeutic and prognostic biomarker." (PMID 29744300, 2018). "Placental growth factor (PGF) has been identified as an OS- and RFS-related IRG, but its role in osteosarcoma is still unclear." (PMID 35463956, 2022).
pulmonary hypertension (5 papers, 2014 to 2025). Increased pressure within the pulmonary circulation due to lung or heart disorder. "Moreover, the association between angiogenesis and pulmonary hypertension in SCD is also suggested by the demonstration of the prominent role of PlGF (Placental Growth Factor) in the pathogenesis of this condition." (PMID 26648000, 2015). "Exposure to extracellular heme in SCD can also augment the expression of placental growth factor (PlGF) and interleukin-6 (IL-6), with important consequences to enthothelin-1 (ET-1) secretion and pulmonary hypertension, and potentially the development of renal and cardiac dysfunction." (PMID 33584641, 2020).
sarcoma (5 papers, 2012 to 2019). A usually aggressive malignant neoplasm of the soft tissue or bone. "The level of GPR64 was higher in ewing sarcoma than other mesenchymal neoplasms, and GPR64 induces placental growth factor (PGF) and metalloproteinase (MMP1) expression." (PMID 31412816, 2019).
asthma (4 papers, 2014 to 2024). "Glutathione S‐transferase omega‐1 (GSTO1), leukocyte immunoglobulin‐like receptor subfamily B member 4 (LIRB4), and placental growth factor (PIGF) were associated with a greater risk of childhood asthma." (PMID 38730525, 2024).
Cerebral ischemia (4 papers, 2014 to 2022). Restriction of arterial blood supply to the brain associated with insufficient oxygenation to support the metabolic requirements of the tissue. "BMSCs overexpressing glial cell-derived neurotrophic factor (GDNF) and placental growth factor (PlGF) display better neuroprotective effects in the rodent model of ICH and cerebral ischemia." (PMID 35769327, 2022).
cervical cancer (4 papers, 2014 to 2020). A primary or metastatic malignant neoplasm involving the cervix. "The placental growth factor (PLGF) has for example been reported to affect cervical cancer BVD and, concomitantly, its progression and metastasis." (PMID 27126599, 2016). "PGF and TNFAIP2 are important angiogenic factors, which were abnormal expression in cervical cancer (CC)." (PMID 33109108, 2020).
chronic obstructive pulmonary disease (4 papers, 2008 to 2017). A chronic and progressive lung disorder characterized by the loss of elasticity of the bronchial tree and the air sacs, destruction of the air sacs wall, thickening of the bronchial wall, and mucous accumulation in the bronchial tree. "The increased expression of placental growth factor (PlGF) in chronic obstructive pulmonary disease and allergy-related asthma suggests its role in the pathogenesis of these diseases." (PMID 28220848, 2017).
Down syndrome (4 papers, 2012 to 2019). "Several studies (for example) have shown that maternal serum placental growth factor (PlGF) is a marker of Down syndrome in the first trimester." (PMID 26237388, 2014).
esophageal cancer (4 papers, 2017 to 2021). A primary or metastatic malignant neoplasm involving the esophagus. "In line with this hypothesis, Chen and coworkers observed higher levels of Placental Growth Factor (PLGF) and Metalloproteinase (MMP9) in metastatic than in non-metastatic esophageal cancer." (PMID 28930282, 2017).
glaucoma (4 papers, 2013 to 2021). Increased pressure in the eyeball due to obstruction of the outflow of aqueous humor. "Ten’s research showed that the expression of IL-2, IL-6, monocyte chemoattractant protein-1 (MCP-1), and placental growth factor (PlGF) were significantly up-regulated in the intraocular fluid of RP patients, and the level of IL-8 was higher in presence of glaucoma." (PMID 34399712, 2021).
intrahepatic cholangiocarcinoma (4 papers, 2021 to 2023). A carcinoma that arises from the intrahepatic bile duct epithelium in any site of the intrahepatic biliary tree. "For example, a subset of quiescent cancer-associated fibroblasts (CAFs) was found to be enriched in the tissue culture of intrahepatic cholangiocarcinoma (ICC) after the blockade of placental growth factor (PIGF)." (PMID 34572523, 2021).
pregnancy disorder (4 papers, 2016 to 2024). A disorder that is related to pregnancy. "The sFlt-1 (soluble fms-like tyrosine kinase-1)/PlGF (placental growth factor) ratio serves as a clinical biomarker to predict the hypertensive, placenta-derived pregnancy disorder pre-eclampsia which is often associated with placental dysfunction and fetal growth restriction." (PMID 35846340, 2022).
bladder cancer (3 papers, 2020 to 2024). "We found that PGF is an additional pro-angiogenic factor in bladder cancer, complementing the well-known role of VEGFA." (PMID 39628692, 2024). "Together, this study identified four prognostic hub immune-related genes, including MMP9, IGF1, CXCL12 and PGF, which might play a vital role in bladder cancer development." (PMID 32675942, 2020). "Future works should focus on developing drugs specifically inhibiting PGF signaling or, ideally, PGF and VEGFA, and on exploring the synergistic effects of combining these drugs with immunotherapy for more effective clinical treatments of bladder cancer." (PMID 39628692, 2024). "There is no report on the roles of OLR1, PGF, or SH3BP2 in outcomes of bladder cancer." (PMID 33888644, 2021).
choroidal neovascularization (3 papers, 2016 to 2024). An eye disorder described by the growth of new blood vessels that originate from the choroid through a break in the Bruch membrane into the sub–retinal pigment epithelium (sub-RPE) or subretinal space. "In wet AMD, accelerated by vascular endothelial growth factor (VEGF) and placental growth factor (PLGF), choroidal neovascularization (CNV) occurs in the macula." (PMID 38796619, 2024).
dementia (3 papers, 2023 to 2025). Loss of intellectual abilities interfering with an individual's social and occupational functions. "Interestingly, six proteins (NEFL, WNT9A, IL17D, IGFBP2, KLK4, and PGF) were repeatedly selected in both diagnostic models that classified dementia from both cognitively normal controls and MCI." (PMID 37175824, 2023). "The CSF expression level of PGF was also reported to be increased in different types of dementia, including AD and vascular dementia; however, PGF showed higher accuracy in distinguishing frontotemporal dementia." (PMID 37175824, 2023). "Notably, NEFL, WNT9A, IL17D, IGFBP2, KLK4, and PGF proteins were included in both models that differentiated dementia from either cognitively normal controls or MCI." (PMID 37175824, 2023). "Indeed, twenty of the differentially expressed proteins in dementia compared with MCI were enriched in the pathways regulating angiogenesis and involved in the VEGFA–VEGFR2 signaling pathway, including the placental growth factor (PGF)." (PMID 37175824, 2023).
liver cancer (3 papers, 2012 to 2024). An epithelial or non-epithelial malignant neoplasm that arises from the liver. "Consequently, JUN is predicted to regulate PGF expression, potentially promoting the migration of liver cancer cells." (PMID 39484208, 2024).
proliferative diabetic retinopathy (3 papers, 2019 to 2022). Advanced retinopathy due to diabetes mellitus characterized by the formation of new vessels in the retina. "In this context we investigated vitreous protein levels, including placental growth factor (PlGF), angiopoietin-2 (ANG2) and vascular endothelial growth factor (VEGF), in patients with proliferative diabetic retinopathy (PDR) with variable disease severities, and after anti-VEGF pre-treatment." (PMID 36473885, 2022).
renal cell carcinoma (3 papers, 2015 to 2024). "Using the TCGA RNA-Seq dataset, we found that while two key pro-angiogenic ligands, VEGFA and PGF, were up-regulated in renal cell carcinoma, they were down-regulated in primary prostate adenocarcinoma (b for prostate, f for kidney)." (PMID 26341082, 2015).
trisomy 21 (3 papers, 2023 to 2025). A chromosomal disorder consisting of the presence of an extra chromosome 21. "A few of these markers have been measured in maternal blood for the screening of trisomy 21 angiogenic factors, such as placental growth factor (PlGF), which was more recently described as being decreased in trisomy 21-affected pregnancies." (PMID 37108840, 2023).
ALLergies (2 papers, 2021 to 2022). "Pathways related to intracellular signalling pathway, stress response, VEGF and MTOR related, the latter showed in the last years to be related with allergy; and oxidative phosphorylation are up-regulated, like FOXP1, SERPIN family, SOD2, caspase family, PGF, CYB5B, SERP1 and SLC25A4." (PMID 34784380, 2021).
fibrosarcoma (2 papers, 2014 to 2016). A malignant mesenchymal fibroblastic neoplasm affecting the soft tissue and bone. "In a murine model of fibrosarcoma, PlGF (placental growth factor), a ligand of VEGFR-1, showed important effects on vascular remodelling and normalization, altering tumour growth." (PMID 25236925, 2014).
heart defects (2 papers, 2014 to 2022). "In the maternal serum of women carrying fetuses with major heart defects associated primarily with conotruncal and septal-valve defects, maternal serum placental growth factor (PlGF) was decreased and soluble fms-like tyrosine kinase-1 (sFlt-1) increased, suggesting impaired placental angiogenesis." (PMID 25426076, 2014). "Previous studies have reported that in cases of isolated major fetal heart defects, maternal serum placental growth factor (PIGF) decreases at 11–13 weeks of gestation, which indicates that placental angiogenesis was impaired in the first trimester of pregnancy." (PMID 36233829, 2022).
hypertrophic cardiomyopathy (2 papers, 2022 to 2024). A condition in which the myocardium is hypertrophied without an obvious cause. "The high expression of the PGF gene was significantly enriched in signaling pathways such as hypertrophic cardiomyopathy, neuroactive ligand-receptor interaction and fatty acid metabolism." (PMID 36276937, 2022).
kidney cancer (2 papers, 2023 to 2026). Primary or metastatic malignant neoplasm involving the kidney. "The identified target diseases for PGF inhibitors included adrenocortical carcinoma, kidney cancers, liver hepatocellular carcinoma, stomach adenocarcinoma, and uveal melanoma." (PMID 37508400, 2023).
lung fibrosis (2 papers, 2019 to 2021). "The data highlight the enhanced inducible cytokine CXCL5 involved in neutrophil recruitment, tissue remodeling and COPD, and placental growth factor (PGF) which is induced in the lung hyperoxia response, involved in macrophage polarization and angiogenesis, and exacerbates pulmonary fibrosis." (PMID 33613309, 2021).
periodontal disease (2 papers, 2024 to 2025). "This study aimed to evaluate the association between gingival crevicular fluid (GCF) levels of placental growth factor (PlGF) and soluble fms-like tyrosine kinase-1 (sFlt-1) and sPTB risk and to assess their correlation with periodontal disease severity during early pregnancy." (PMID 40800007, 2025).
placenta accreta (2 papers, 2018 to 2022). The clinical condition in which any part of the placenta invades and is inseparable from the uterine wall. "Elevated first-trimester serum placental growth factor (PIGF) was significantly associated with placenta accreta, indicating the potential role of PIGF in identifying high-risk pregnancies for placenta accreta." (PMID 35860796, 2022). "The findings of this study suggest that a decrease in vascular endothelial growth factor, placental growth factor and soluble fms-like tyrosine kinase 1 levels may be related to placenta percreta etiopathogenesis." (PMID 28903888, 2018).
skin cancer (2 papers, 2020 to 2024). "For example, impaired tumor vascularization of skin cancer xenografts, as determined by altered blood vessel morphology and decreased expression of proangiogenic factors (VEGF, placental growth factor (PlGF), angiopoietin-2), has been shown in nude mice treated with the CB2 receptor agonist JWH-133." (PMID 38255884, 2024).
white matter hyperintensities (2 papers, 2025). "We investigated the association between white matter hyperintensities (WMH) severity and fluid biomarkers, including cerebrospinal fluid (CSF) neurofilament light chain and plasma placental growth factor (PlGF) levels." (PMID 41154596, 2025).
Acute fatty liver of pregnancy (1 paper, 2021). "Acute fatty liver of pregnancy (AFLP) is characterized by elevated circulating sFlt-1 (soluble Fms-like tyrosine kinase-1), although the free circulating levels of its ligand, PlGF (placental growth factor) are not decreased." (PMID 34176292, 2021).
acute leukemia (1 paper, 2026). A clonal (malignant) hematopoietic disorder with an acute onset, affecting the bone marrow and the peripheral blood. "GF is associated with a high mortality rate; we recently analyzed 243 patients with acute leukemia undergoing HSCT from various donors (~40% UD) who were complicated by pGF." (PMID 41109900, 2026).
cataract (1 paper, 2018). Partial or complete opacity of the crystalline lens of one or both eyes that decreases visual acuity and eventually results in blindness. "Then the suspension array method was employed to measure sVEGFR-1, sVEGFR-2, VEGF, and placental growth factor (PlGF) in aqueous humor samples from the 24 AMD patients and 13 cataract patients (as controls)." (PMID 30534004, 2018).
colitis (1 paper, 2023). Inflammation of the colon. "Other organ-specific irAEs were associated with stem cell factor (colitis), leukemia inhibitory factor and placental growth factor (both with myositis), and B and T-lymphocyte attenuator (dermatitis)." (PMID 36900420, 2023).
cystic fibrosis (1 paper, 2021). Autosomal recessive disorder caused by pathogenic variants in the CFTR gene (cystic fibrosis transmembrane conductance regulator), which encodes a chloride and bicarbonate channel expressed in epithelial cells, and follow the diagnosis criteria. "Angiogenic growth factors VEGF-A, VEGF-C, bFGF, and placental growth factor (PLGF) have been found to be increased in cystic fibrosis patients." (PMID 33230600, 2021).
dyslipidaemia (1 paper, 2024). "Another study provided robust evidence supporting the notion that dyslipidaemia promotes the development of DR through increased secretion of vascular endothelial growth factors A, C and D, as well as placental growth factor in patients with DR." (PMID 38874277, 2024).
endometrial adenocarcinoma (1 paper, 2023). "PGF-PTGFR autocrine loop has been shown to have various functions in the tumorigenesis of endometrial adenocarcinoma." (PMID 38188684, 2023).
familial hypercholesterolemia (1 paper, 2023). An inheritable form of hyperlipidemia, in which there are excess lipids in the blood. "Analysis of Open Targets and other databases indicated evidence of drug development, including phase II-IV trials, for 6 proteins (PGF, ASGR1, F2R, TFPI, tenascin, and MMP3), with 3 related to CVD outcomes or traits (F2R for MI, TFPI for ICH, and ASGR1 for familial hypercholesterolemia)." (PMID 37940228, 2023).
ocular cancer (1 paper, 2020). A benign or malignant neoplasm affecting the structures of the eye. "PGF, a homologue of VEGF, plays an important role in placental development, and has been shown to be involved in pathological angiogenesis both in ocular and non-ocular cancers." (PMID 32290826, 2020).